TNF (tumor necrosis factor)
Diseases named in the same sentence as TNF in open-access papers (continued):
Sharing a sentence is not in itself a finding about the gene and the disease.
myocardial infarction (continued). "Isoproterenol-induced myocardial infarction significantly amplified HSP-60 and inflammatory markers (TNF-α, IL-1β, and NFκB) as compared with normal rats." (PMID 31109132, 2019). "We compared myocardial infarct size, serum levels of cTnI, and expression of HMGB1, TNF-α, and IL-6 in the myocardium and serum in all groups after 120 min of reperfusion." (PMID 31344138, 2019). "Linkage of the TNF-α AA genotype has been reported with the increased TNF-α expression, rheumatic heart disease, myocardial infarction and ischemic stroke." (PMID 30635365, 2019). "In particular, TLR-4 and its downstream targets such as TNF-α and i-NOS are found to facilitate the inflammatory reaction in clinical ischemic condition, i.e. myocardial infarction." (PMID 30356256, 2018). "Tumor Necrosis Factor (TNF), Interleukin-1β (IL-1β) and Interleukin-6 (IL-6) are markedly increased during myocardial infarction." (PMID 29166391, 2017). "These PICs include tumor necrosis factor-alpha (TNF-α), interleukin-1β (IL-1β) and IL-6, which are released into the circulation early after myocardial infarction (MI)." (PMID 25984330, 2014). "Yet another finding of our study was the highly significant positive correlation between TNF-α and lipoprotein (a) in the CAD-prone North Indian patients with acute myocardial infarction." (PMID 20532435, 2010). "High TGF-β1 levels are also not a direct cause of heart attack, although TGF-β1 levels are linked to specific biochemical risk factors in early-onset CAD cases, including circulating TNF, triglycerides, and platelets." (PMID 41150748, 2025). "Similarly, infliximab, a TNF-α inhibitor, has been studied to improve inflammation AMI induced in a porcine myocardial infarction model." (PMID 41291938, 2025). "In a myocardial infarction (MI) mouse model induced by left anterior descending (LAD) coronary artery ligation, ALA administration reduced infarct size and the serum levels of IL-1β, TNF-α, and creatine kinase-myocardial band (CKMB)." (PMID 40699721, 2025). "These preliminary experimental data showed that the high levels of TNF-α, TLR4, NF-κB, and ROS might affect the formation of collaterals in myocardial infarction mice." (PMID 41278503, 2025). "HUMSCs-derived exosomes loaded with a miR-29b mimic suppressed expression of interleukin 1β (IL-1β)/-6, tumor necrosis factor alpha (TNF-α), and inducible nitric oxide synthase (iNOS) and reduced myocardial fibrosis when delivered through a microneedle patch to a myocardial infarction." (PMID 40676634, 2025). "As a result of weak GMA intervention, the expression of TLR4, TRAF6, NF-κB, and TNF-α was significantly decreased, the expression of MyD88 and MCP-1 was increased, the inflammatory response was blunted, the area of myocardial infarction was reduced, and cardiac function was improved." (PMID 38197985, 2024). "In particular, the TNF and IL1 families are involved in inflammatory cell accumulation, platelet aggregation, vulnerable plaque formation, cardiomyocyte apoptosis, and adverse remodeling after myocardial infarction." (PMID 38541966, 2024). "This enzyme is activated by different molecules, such as pro-inflammatory interleukin-1α (IL-1α) and tumor necrosis factor α (TNF-α), both of which are produced in response to myocardial ischemia, and contributes to myocardial infarction and reperfusion injury." (PMID 36835616, 2023). "Another study showed that 8-HETE levels were higher in patients that had experienced a myocardial infarction relative to matched controls, and 8-HETE was significantly positively correlated with the pro-inflammatory cytokine tumor necrosis factor-alpha (TNF-α)." (PMID 36984892, 2023). "Increased proinflammatory biomarkers such as tumor necrosis factor (TNF)-α, interleukin (IL)-1β, IL-6, and monocyte chemoattractant protein-1 are strongly related to inappropriate healing of the myocardium after myocardial infarction and progressive cardiac dysfunction." (PMID 38034376, 2023).
myocardial infarction (continued). "Levels of TLR2, TLR3, TLR4, TNF-α, sTNFR-1, and sTNFR-2 were remarkably increased (P < 0.001), and EPCs and VEGF were remarkably lowered (P < 0.001) in the elderly patients with recurrent myocardial infarction after coronary stent implantation." (PMID 35425840, 2022). "Administration of emodin reduced myocardial infarct size in a dose-dependent manner in mice with AMI, significantly inhibited tumor necrosis factor (TNF)-α expression and NF-κB activation in localized myocardial infarct areas, and inhibited cardiomyocyte apoptosis by inhibiting caspase-3 activation." (PMID 36618923, 2022). "Activation of a trans-valvular Impella CP pump, but not VA-ECMO, before reperfusion reduced myocardial infarct size and attenuated an increase in TNF-a and IL-6 levels and MMP-9 levels and activity in the LV and renal cortex." (PMID 33782857, 2022). "Several trials were able to show that not only iVNS dampens inflammatory reactions, but also taVNS leads to decreased serum levels of IL 1β, IL 6, TNF-α, and HMGB-1 in patients with myocardial infarction or atrial fibrillation compared to sham-stimulated controls." (PMID 34599686, 2022). "It suppresses p38 MAPK signaling pathway, and reduces arrhythmogenesis following myocardial infarction, and enhances cardiac function.It inhibits the expression of TLR4, MyD88, GM-CSF, IL-1β, TNF-α, and COX-2, and attenuates LPS-mediated TLR4-NF-κB pathway activation." (PMID 33868227, 2021). "TNF-α is not constitutively expressed in normal hearts, while in acute myocardial infarction (AMI) the elevated TNF-α expression in cardiomyocytes is damaging and contributes to cardiac remodelling." (PMID 33086718, 2020). "MPs from activated macrophages could carry tumor necrosis factor-alpha (TNF-α) and contribute to the propagation of inflammatory signals leading to myocardial infarction." (PMID 32962240, 2020). "Proinflammatory cytokines like interleukin-1 (IL-1), interleukin (IL-6), interferon-gamma (IFN-γ) and tumor necrosis factor-α (TNF-α) predict the cardiovascular risks including coronary artery disease, myocardial infarction, chronic heart failure, peripheral arterial disease and unstable angina." (PMID 31491986, 2019). "Thereby, among patients with RA, responders to anti-TNFα biologic therapies could markedly reduce the risk of myocardial infarction (MI) when compared to non-responders." (PMID 29216228, 2017). "TNFα remained moderately increased 3 days post infarction with continuous moderate increase after 1 month FUP in both groups, most probably due to developing chronic phase of myocardial infarction." (PMID 28299177, 2016). "However, the pretreatment reduced myocardial infarct size and TUNEL-positive cell rate, as well as decreased the levels of cleaved caspase-3, cytoplasm cytochrome C, CK, LDH, MDA, and TNF-α." (PMID 26265983, 2015). "In this study, we have predicted a stable equilibrium for homeostasis, which means without myocardial infarction or following small injury stimuli, macrophage densities and concentrations of IL-1, IL-10, and TNF-α should stay at the equilibrium." (PMID 23134700, 2012). "TNF-α can up-regulate ICAM-1 expression of MSC and enhance the cells’ migration ability, and it can modify characteristics of MSC to improve their engraftment in experimental myocardial infarction." (PMID 22296115, 2012). "In addition, it has been observed that kaempferol pretreatment led to a decrease in myocardial infarct size, along with decreased levels of cytoplasmic cytochrome C, creatine kinase (CK), cleaved caspase-3, lactate dehydrogenase (LDH), tumor necrosis factor-alpha (TNF-α), and malondialdehyde (MDA)." (PMID 38731498, 2024). "COPD—Chronic obstructive pulmonary disease, NAFLD—Non-alcoholic fatty liver disease, MI—Myocardial infarction, PGE2- Prostaglandins, MMP—Matrix metalloproteinase, IL—Interleukin, TNF-α—tumor necrosis factor-alpha, CRP—C-reactive protein." (PMID 36361416, 2022).
myocardial infarction (continued). "TNF-α is not expressed in normal cardiomyocytes, but after myocardial infarction, the ischemia and anoxia activate cardiomyocytes and myocardial mononuclear macrophages, which will produce large amounts of TNF-α in the myocardium in the infarcted zone and the infarction border zone." (PMID 31205590, 2019). "At present, it has been reported that TNF-α antagonism is most likely not beneficial in the treatment of acute myocardial infarction because it decreases systemic inflammation while increasing platelet activation, which does not affect peripheral vasomotor or fibrinolytic function." (PMID 28479928, 2017). "Furthermore, multiple studies have shown that increased TNF-α production and/or activation of IKK-β/NF-κB are the key mediators of inflammation, oxidative stress and vascular endothelial dysfunction in ischemia reperfusion model of myocardial infarction." (PMID 24324809, 2013). "Furthermore, high concentrations of some inflammatory mediators [e.g., tumor necrosis factor α (TNF-α), interleukin (IL)-1, IL-6, IL-17, and C-reactive protein] have been associated with increased risk of myocardial infarction and non-traumatic fragility fractures." (PMID 35163560, 2022). "Dex increased TNF-α and IFN-γ production in splenic T cells and improved cardiac function in a murine model of myocardial infarction (MI), which suggests a novel strategy for the treatment of MI using Dex-based therapeutics." (PMID 31615107, 2019). "The results demonstrated that compared to MI/R, etanercept reduced myocardial infarction area, myocardial myeloperoxidase (MPO) levels, serum creatinine kinase (CK) and lactate dehydrogenase (LDH) levels, and both serum and myocardial TNF-α production." (PMID 25260027, 2014). "In a randomized control trial in patients with acute myocardial infarction, a short duration of treatment with vitamin D has significant impact on weakening the rise of CRP and IL-6 (but not TNF-α)." (PMID 32153865, 2018). "Furthermore, the expression of IL‐8 and TNF did not correlate with several markers of CVD severity, including the number of coronary arteries with significant stenosis, New York Heart Association (NYHA) class 10, or the number of previous myocardial infarctions." (PMID 26749303, 2016). "The JJYNJ treated CAL group also showed a diminishment (p < 0.05) of TGF-β1 and TNF-α mRNA transcription; AT1R mRNA expression in left ventricular tissue was decreased 4 weeks after myocardial infarction but showed no obvious changes." (PMID 26185521, 2015). "Paired comparisons of subgroups with stable angina, unstable angina, and acute myocardial infarction (AMI) revealed significant variation in plasma levels of apoCIII, TNF-α and hs-CRP (P < 0.01), but not among subgroups with mild, moderate and severe stenosis (P > 0.05)." (PMID 30053815, 2018). "We have previously shown that the overall risk of early myocardial infarction was similar between our anti-TNF and nonbiologic DMARD groups, although patients whose RA had responded to the initial anti-TNF agent at 6 months had lower rates of myocardial infarction." (PMID 20662063, 2010). "Likewise, the Framingham Heart Study revealed that elevated baseline levels of TNF-α, IL-6, and CRP in individuals without a history of acute myocardial infarction (MI) are associated with a significantly increased long-term risk of developing HF, irrespective of MI occurrence." (PMID 40814000, 2025). "Columns 3–6: Genotypic frequencies of TNFα-308 in CHD patients and non-CHD (control) patients from twenty studies (indexed i) and for two CHD phenotypes (indexed j), namely coronary stenosis (CS) and myocardial infarction (MI)." (PMID 26401451, 2015).
psoriatic arthritis (431 papers, 2005 to 2026). Joint inflammation associated with psoriasis. "This complex scenario presents a dilemma in balancing the management of psoriatic arthritis with anti-TNFα therapy and mitigating the risk of bacterial infection." (PMID 38883009, 2024). "A retrospective study on the treatment of psoriatic arthritis and the risk of herpes zoster included 3,128 patients to explore the association of traditional antirheumatic drugs and TNF inhibitors with herpes zoster." (PMID 39070789, 2024). "Psoriatic arthritis (PsA) is a chronic, immune-mediated inflammatory condition, and the proinflammatory cytokine tumor necrosis factor-α (TNF-α) plays a major pathogenic role in the development and progression of PsA." (PMID 37090269, 2023). "For this reason, anti-tumor necrosis factor therapies have become a hallmark option for psoriatic arthritis patients." (PMID 37511975, 2023). "Psoriatic arthritis (PsA) is an inflammatory rheumatic disease, mediated in part by TNFα and associated with bone loss." (PMID 34010320, 2021). "For patients with psoriatic arthritis or coexisting cardiovascular risk factors, for example, selecting TNF-α inhibitors allows co-management of multiple disease processes." (PMID 34816130, 2021). "Meta-analyses exhibited that TNF-α −857T allele was associated with increased susceptibility to gastric cancer, type 1 diabetes, and psoriatic arthritis." (PMID 31652851, 2019). "In the case of obese psoriatic arthritis, weight reduction was associated with greater response to TNF-inhibitor, and weight reduction will also be a reasonable approach to recover the response to the therapies in patients with RA." (PMID 28569167, 2017). "In patients with psoriatic arthritis, the use of anti-TNF-α was associatedwith reduced risk of developing DM (OR = 0.62) compared with the use of otherdisease modifying drugs (except methotrexate)." (PMID 28099601, 2016). "Rare cases have also been reported where treatment with tumor necrosis factor (TNF)-α inhibitors was associated with paradoxical development of sarcoidosis, usually in patients with rheumatologic diagnoses including psoriatic arthritis." (PMID 25285443, 2014). "Accordingly, we performed a meta-analysis to provide new evidence that SNPs in the TNFα gene promoter region alter not only the risk of psoriasis vulgaris (PsV) or psoriatic arthritis (PsA) but also of PsV&PsA." (PMID 23717605, 2013). "We have performed a case-control association study of three TNF-alpha gene polymorphisms in a group of Romanian psoriatic arthritis patients versus ethnically matched controls." (PMID 21954344, 2011). "The present study shows that TNF-alpha gene promoter polymorphism −857C/T is associated with the susceptibility to psoriatic arthritis in Romanian population at the individual level and in combined haplotypes with −238G/A and −308G/A SNPs." (PMID 21954344, 2011). "Our aim in this study was to investigate the association of three TNF-alpha gene promoter polymorphisms with psoriatic arthritis in a Romanian group of patients." (PMID 21954344, 2011). "Tumor necrosis factor alpha (TNF-alpha) is an important pro-inflammatory cytokine implicated in the pathogenesis of psoriatic arthritis." (PMID 21954344, 2011). "The aim of this study was to assess persistence with first-course and second-course treatment with anti-TNF agents in a prospective cohort of psoriatic arthritis patients and to identify factors associated with and reasons for drug discontinuation." (PMID 19356232, 2009). "Psoriatic arthritis is associated with increased vascular changes due to the secretion of pro-inflammatory cytokines, such as tumor necrosis factor (TNF)-alpha and vascular endothelial growth factor, which may contribute to the development of peliosis hepatis." (PMID 40909070, 2025). "Furthermore, tumor necrosis factor-α (TNF-α) gene polymorphisms are associated with disease susceptibility and response to etanercept (TNF-α inhibitor) in psoriatic arthritis patients." (PMID 38638121, 2024).
psoriatic arthritis (continued). "For instance, in patients with psoriatic arthritis or concurrent cardiovascular risk factors, opting for TNF-α inhibitors may enable the management of multiple disease processes concurrently." (PMID 39240834, 2024). "However, a national cohort from Australia suggested that anti-TNF therapy was associated with a reduction in major cardiovascular events in rheumatoid arthritis, psoriatic arthritis, and ankylosing spondylitis." (PMID 35160136, 2022). "Interleukin-17 and IL-12 along with the TH1 cytokines (TNF-α, IL-1B, and IL-10) have been found in higher levels in psoriatic arthritis synovium and IL-17 and IL-23 have been implicated in the potentiation of osteoclastogenesis and bone erosion in psoriatic arthritis joints." (PMID 23209897, 2012). "Adalimumab, a human monoclonal antibody targeting TNF-α, is approved for treatment of multiple inflammatory diseases, including psoriatic arthritis." (PMID 41362871, 2026). "For serious infections, guidelines recommend TNF-α inhibitor discontinuation, antibiotic initiation, and low-dose corticosteroids or NSAIDs for psoriatic arthritis management." (PMID 41362871, 2026). "For instance, patients with psoriatic arthritis receiving tumor necrosis factor inhibitors (TNFi) achieved anti-SARS-CoV-2 IgG levels comparable to healthy controls following the BNT162b2 vaccine." (PMID 40735320, 2025). "When the rash first appeared, the patient was three doses into a weekly tumor necrosis factor alpha blocker, adalimumab, regimen to treat her psoriatic arthritis." (PMID 41328145, 2025). "The successful management of this case with etanercept highlights the potential for TNF inhibitors to safely treat psoriatic arthritis complicated by peliosis hepatis." (PMID 40909070, 2025). "Bimekizumab is the first dual targeting IL‐17A/F antibody, and the 16‐week American College of Rheumatology 50% improvement rate (ACR50) in TNF‐α inhibitor‐refractory psoriatic arthritis was 46% in one study." (PMID 40529617, 2025). "Biologics that inhibit TNF-α, p40 IL-12/23, and IL-17 are also approved for the treatment of psoriatic arthritis." (PMID 40109802, 2025). "In contrast, biologic therapy, such as etanercept, a tumor necrosis factor inhibitor, proved effective in our case in improving both liver function and psoriatic arthritis symptoms." (PMID 40909070, 2025). "Among the four patients with psoriatic arthritis, two received anti-TNF-α, and two received anti-IL-23 therapy." (PMID 40699767, 2025). "IL-17 inhibitors have demonstrated efficacy in psoriatic arthritis, not only in TNF-naïve patients but also in those with inadequate responses or intolerance to TNF inhibitors." (PMID 40615873, 2025). "Credit: This table was created by the authors using data from multiple published sources to compare JAK inhibitors and TNF inhibitors in psoriatic arthritis." (PMID 40949078, 2025). "Bimekizumab has demonstrated robust efficacy in both psoriatic arthritis and axial spondyloarthritis, encompassing both radiographic and non-radiographic forms, including patients who have previously failed anti-TNF therapy." (PMID 40076933, 2025). "In a study with seven ERA and two juvenile psoriatic arthritis cases, after one or two anti-TNF therapies failed (primary or secondary resistance to anti-TNF), secukinumab achieved inactive clinical disease." (PMID 40364197, 2025). "Interleukin-23 inhibitors and TNF-alpha inhibitors are classes of biologic medications used to manage psoriatic arthritis." (PMID 41328145, 2025). "Adalimumab is a recombinant human anti-TNF monoclonal antibody used in the treatment of various immune-mediated diseases such as psoriatic arthritis, rheumatoid arthritis, and Crohn’s disease." (PMID 39881908, 2024). "Achievements with TNF inhibitors have led to significant improvements across multiple aspects of psoriatic arthritis." (PMID 38792999, 2024).